FGF21 (fibroblast growth factor 21)
Diseases named in the same sentence as FGF21 in open-access papers (continued):
Sharing a sentence is not in itself a finding about the gene and the disease.
Insulin resistance (continued). "The results show that the nano-EE5 can improve hyperglycemia, insulin resistance, and plasma fibroblast growth factor 21 (FGF 21) resistance." (PMID 30246020, 2018). "Collectively, we demonstrated the potential protection of PGE1 on insulin resistance in renal tubules via autophagy-dependent FGF21 pathway in preventing the progression of DN." (PMID 29311680, 2018). "It was reported that the defective autophagy had a protective effect on insulin resistance in HFD-fed obese mice by promoting FGF21 expression." (PMID 29311680, 2018). "The results demonstrated that blocking FGF21 signal is indeed responsible for the amelioration of insulin resistance by PGE1 in HK-2 cells." (PMID 29311680, 2018). "PGE1 inhibited excessive autophagy and insulin resistance, and increased the expression of FGF21 in kidney tubule in T2DM rats." (PMID 29311680, 2018). "Plasma FGF-21 levels increase in obese subjects and correlate positively with homeostasis model assessment of insulin resistance (HOMA-IR)." (PMID 29445355, 2018). "FGF21 is an intriguing hepatokine as it is generally considered as beneficial; however, some data indicate either states of FGF21 resistance or deleterious effects, as suggested by the very high FGF21 plasma levels observed in patients with insulin resistance." (PMID 30200408, 2018). "We confirmed the results that inhibition of autophagy resulted in an increased expression of FGF21 protein in HK-2 cells, which mediated the inhibition of insulin resistance by PGE1." (PMID 29311680, 2018). "To confirm the role of PGE1 on DN and mechanisms, we examined the makers of autophagy, insulin resistance, and the FGF21 expression in rat kidney by western blotting." (PMID 29311680, 2018). "Results from western blotting and immunohistochemistry indicated that PGE1 remarkably restored autophagy, insulin resistance and the FGF21 expression in rat kidney of type 2 diabetes mellitus (T2DM)." (PMID 29311680, 2018). "We also demonstrated that this decrease of autophagy and consequent upregulation of downstream molecular fibroblast growth factor-21 (FGF21) resulted in the recovery of insulin resistance by PGE1." (PMID 29311680, 2018). "In fact, FGF21 levels were positively correlated with glucose levels (r = 0.197, p = 0.048), insulin levels (r = 0.224, p = 0.038), and insulin resistance, measured as HOMA‐IR, (r = 0.427, p = 0.005) in the studied cohort." (PMID 30043445, 2018). "Numerous studies report that serum concentrations of FGF-21 are elevated in obese individuals and positively correlate with insulin resistance, BMI, % fat mass and circulatory concentrations of leptin and LDL." (PMID 29760587, 2018). "Consistent with this, Fgf21 can rescue Dnmt3a-mediated insulin resistance, and DNA methylation at the FGF21 locus was elevated in human subjects with diabetes and correlated negatively with expression of FGF21 in human adipose tissue." (PMID 29091029, 2017). "FGF21 is related to metabolism, stress response, mitochondria function, and insulin resistance, as serum levels of FGF21 are elevated in certain types of mitochondria dysfunction, particularly in the muscle." (PMID 28373915, 2017). "In diabetic rodents and monkey, FGF21 is considered an effective metabolic regulator of glucose and lipid homeostasis in the context of insulin resistance, glucose intolerance and dyslipidemia." (PMID 28781774, 2017). "FGF21 is a pleiotropic secretion protein, which possesses multiple metabolic benefits including ameliorating insulin resistance, improving hepatic lipid accumulation, and extending lifespan." (PMID 29109955, 2017). "White pitaya juice and purified peel betacyanins (PPBNs) improved insulin resistance through decreasing fibroblast growth factor-21 (FGF-21) expression and increasing level of FGF-21 related genes (Klb, FGFR2, Egr1 and cFos) in the liver." (PMID 28886195, 2017).
Insulin resistance (continued). "Because of the challenges in determining insulin resistance in dolphins, we decided to investigate hormonal changes in the insulin sensitizing FGF21/adiponectin/ceramide axis that would be consistent with improving insulin sensitivity." (PMID 27148164, 2016). "More mechanistic studies are needed to define the signaling mechanisms linking FGF21 with insulin resistance." (PMID 27190511, 2016). "In summary, the main finding of our study was that serum FGF21 was increased in response to insulin resistance in AN." (PMID 27190511, 2016). "It was proposed that the elevated level of FGF21 was attributed to FGF21 resistance, a phenomenon reminiscent of hyperinsulinemia and insulin resistance." (PMID 25850006, 2015). "The present study is the first to report the modulatory action of FGF21, probably via GH signaling, in the pathogenesis of insulin resistance, and its regulatory role in pancreatic islet response to insulin resistance." (PMID 25811804, 2015). "Although KD promotes FGF21 expression in the liver, such a diet has also been shown to induce hepatic insulin resistance." (PMID 25973847, 2015). "Administration of FGF21 exerts beneficial effects including reduction of adiposity, insulin resistance, dyslipidemia, and fatty liver." (PMID 25991671, 2015). "In conclusion, our findings support that FGF21 is an obligatory metabolic regulator in pancreatic islets, which sheds new light into the pathophysiological role of FGF21 in insulin resistance and islet dysfunction." (PMID 25811804, 2015). "Since oxidative stress is associated with chronic hyperglycemia-induced insulin resistance and a decline in insulin biosynthesis and secretion, we are tempted to speculate that the oxidative stress resistance putatively conferred by FGF21 contributes to the beneficial metabolic actions of FGF21." (PMID 26089880, 2015). "Moreover, systemic administration of FGF21 improves insulin sensitivity and relieves hyperinsulinemia in ob/ob, db/db mice, diet-induced obese mice and diabetic monkeys, which are consistent with our data that loss of FGF21 induces insulin resistance and hyperinsulinemia." (PMID 25811804, 2015). "Diseases related to insulin resistance such as metabolic syndrome and type 2 diabetes mellitus have been related to increased levels of FGF21." (PMID 24883065, 2014). "We searched for further possible explanations of reduced glucose intolerance and, interestingly, found the expression of hepatic FGF21, which has a role in ameliorating insulin resistance, to be markedly decreased in both wild type and KKAy mice." (PMID 25170869, 2014). "In contrast, serum FGF21 levels independently and positively correlated with insulin resistance and serum triglycerides and were inversely related to serum adiponectin." (PMID 24260557, 2013). "KD feeding for 6 days induced both glucose intolerance and insulin resistance and hepatic Fgf21 expression." (PMID 23874946, 2013). "Because the link between FGF21, adiponectin, glucagon, and insulin resistance is very strong, future studies should consider measurements of FGF21 in dolphins." (PMID 24065958, 2013). "In summary, palmitate-induced insulin resistance is associated with myotube loss and impaired expression of three health benefit myokine genes (FNDC5, CTRP15 and FGF21) in C2C12 myotubes." (PMID 23866690, 2013). "Results of the GTT and ITT showed that glucose intolerance and insulin resistance were significantly improved in Fgf21 knockout mice." (PMID 23874946, 2013). "In conclusion, we show that FGF-21 mRNA is increased in skeletal muscle in HIV patients and that FGF-21 mRNA in muscle correlates to whole-body (primarily reflecting muscle) insulin resistance." (PMID 23533568, 2013). "Here, serum FGF19 levels were reduced in HIV-infected patients with metabolic disturbances including hyperglycemia and insulin resistance, whereas FGF21 levels were increased." (PMID 24260557, 2013).
Insulin resistance (continued). "Muscle FGF-21 mRNA correlated positively to all markers of insulin resistance: fasting insulin (r = 0.57, p = 0.0008), homeostasis model assessment (HOMA) score (r = 0.55, p = 0.001), and insulinAUC (r = 0.38, p = 0.02)." (PMID 23533568, 2013). "Serum FGF21 level has been found to be higher in insulin resistance status in both human-based studies and rat experiments." (PMID 23981342, 2013). "As mentioned, FGF21 has direct effects in enhancing skeletal muscle glucose uptake in both rodents and human myocytes and protects human myotubes from palmitate-induced insulin resistance, demonstrating that FGF-21 signals directly in muscle." (PMID 23533568, 2013). "Both serum FGF19 and FGF21 levels are strongly related to insulin resistance and serum levels of adiponectin." (PMID 24260557, 2013). "In regard to the role of FGF21 in lipid metablism and insulin resistance during pregnancy, the current study highlights the need for future study in this population of different races and ethnics." (PMID 24349098, 2013). "Clearly, a great amount of studies are needed to better elucidate the pathophysiological significance of FGF21 up-regulation in pregnancy when hyperglycemia, insulin resistance and dyslipidemia are present." (PMID 24260557, 2013). "This explanation is supported by in vitro models, where FGF-21 is found to protect human myotubes from palmitate-induced insulin resistance, and to increase basal and insulin-stimulated glucose uptake in human myotubes." (PMID 23533568, 2013). "Further studies will be required to investigate the pharmacological effects of FGF21 on impaired glucose metabolism and insulin resistance in pregnancy." (PMID 24260557, 2013). "Metabolically protective cytokines, adiponectin and FGF-21, were increased by over nutrition and weight gain in healthy humans, despite increases in insulin resistance." (PMID 24205333, 2013). "In the present study, the mRNA expression of FGF-21 in liver and adipose tissue was significantly up-regulated in insulin resistance mice induced by HFD-adiponectin knockdown." (PMID 23152772, 2012). "Liraglutide increased adiponectin levels and FGF-21 activity and was sufficient to prevent severe insulin resistance induced by adiponectin knockdown, and thereby also probably improved FGF-21 resistance." (PMID 23152772, 2012). "In conclusion, our work provided a compelling insulin resistance model, in which the combination of HFD and adiponectin knockdown exacerbated insulin resistance and probably also resulted in FGF-21 resistance." (PMID 23152772, 2012). "Acrp30/adiponectin is known to improve insulin resistance and FGF-21 also enhances insulin sensitivity in animals and humans with diabetes." (PMID 23152772, 2012). "Serum FGF21 levels are significantly increased in patients with metabolic diseases having insulin resistance." (PMID 21331285, 2011). "In a previous study that is comparable with our study, ob/ob mice with both hyperglycemia and insulin resistance were given with FGF21 by s.c. once daily with 125 or 750 μg/kg/d for 7 days." (PMID 21673953, 2011). "Serum FGF21 levels are increased in patients with metabolic diseases having insulin resistance, indicating that FGF21 is a metabolic regulator and a biomarker for these diseases." (PMID 21331285, 2011). "Therefore, when FGF21 is used to treat patients with high-fat diet-induced insulin resistance, it should be combined with exercise therapy to repair the FGF21-lipocalin axis and restore their metabolic functions." (PMID 40881124, 2025). "Finally, the progress of FGF21 analog research is summarized in the context of the treatment of insulin resistance." (PMID 40881124, 2025). "Additionally, higher circulating FGF21 concentrations have been reported in individuals with insulin resistance and type 2 diabetes." (PMID 40390366, 2025).
Insulin resistance (continued). "Spearman correlation analysis indicated a positive relationship between FGF-21 and various indicators of insulin resistance (IRI at 0, 60, and 120 min and HOMA) and liver enzymes (ALAT and GGT), along with the visceral adiposity index, triglycerides, and uric acid." (PMID 40559404, 2025). "Moreover, miR-22 expression has been demonstrated to be negatively correlated with FGF21 in adolescents with insulin resistance, where increased miR-22, blunting hepatic FGF21, promotes the worsening of steatosis." (PMID 39859495, 2025). "Furthermore, we found that FGF21/sTGFBR2 gene therapy was dependent on adipose tissue to improve insulin resistance in lipodystrophic mice housed at 30°C, but FGF21 alone improved insulin resistance in lipodystrophic mice at 22°C." (PMID 40663389, 2025). "AhR activation may either exacerbate insulin resistance through the induction of proinflammatory signaling or potentially ameliorate it via activation of metabolic regulators such as FGF21." (PMID 41440753, 2025). "The authors suggested that prolonged exercise might reduce FGF-21 resistance, similar to insulin resistance, thereby decreasing the FGF-21 level." (PMID 39997712, 2025). "However, an up-regulation of FGF-21 in patients living with T2D has been reported and correlates with hepatic and muscle insulin resistance, making it a potential early biomarker of the disease." (PMID 40943107, 2025). "Liver ChREBPβ positively correlated with insulin resistance and FGF21." (PMID 41373582, 2025). "In addition, studies have found that when FGF21 was used to treat mice fed a high-fat diet, insulin resistance was significantly improved." (PMID 39819596, 2025). "By binding to a specific receptor, FGF21 improves systemic insulin resistance and lipid turnover." (PMID 38674916, 2024). "Main outcomes were C-peptide to proinsulin ratio, circulating microRNA 375 (miR375), homeostatic model assessment (HOMA) beta-cell function (B), fatty liver index (FLI), hepatic steatosis index (HSI), HOMA insulin resistance (IR), and circulating fetuin-A and fibroblast growth factor 21 (FGF21)." (PMID 38797835, 2024). "This study indicated that aminoadipic acid levels are elevated in liver of FGF21 KO mice, also supporting the hypothesis that increased insulin secretion and insulin resistance exist in FGF21 KO mice." (PMID 38653921, 2024). "FGF21 also induces the nuclear translocation of nuclear factor erythroid 2-related factor 2 (Nrf2), promoting the expression of antioxidant genes, which alleviates oxidative stress and improves insulin resistance." (PMID 39574905, 2024). "As with insulin resistance, this may suggest a requirement for a supraphysiological dose of FGF21 to meet concentration demands." (PMID 39511582, 2024). "A subgroup analysis of a Phase 3 trial involving patients with type 2 diabetes mellitus and hypertriglyceridemia revealed that pemafibrate decreased the HOMA‐IR level and improved insulin resistance through an increase in the serum fibroblast growth factor 21 level." (PMID 38572327, 2024). "FGF-21 has the ability to inhibit glucagon receptors and improve insulin resistance." (PMID 39296716, 2024). "Interestingly, despite its positive effects, FGF-21 levels are often elevated in states of insulin resistance and T2DM." (PMID 39544568, 2024). "Fetuin-A is also increased in circulation in T2D and, unlike FGF21, causes insulin resistance and proinflammatory cytokine production from adipocytes and macrophages." (PMID 38797835, 2024). "As such, insulin resistance by the liver is speculated to play a role in mediating the higher circulating levels of FGF21 seen in T2D." (PMID 38797835, 2024). "Another study assessed the association between FGF21 and glycohemoglobin, beta-cell function, and insulin resistance among 2 584 patients without hypoglycemic agent treatment." (PMID 36594101, 2023).
Insulin resistance (continued). "However, the function of FGF21 is affected to varying degrees when insulin resistance or insulin signal transduction disorder occurs." (PMID 38069273, 2023). "FGF-21 analogs can regulate blood glucose, decrease blood lipids, and improve insulin resistance." (PMID 37514488, 2023). "HP may be related to the improvement of insulin resistance and the influence of FGF21 on the afferent pathway of stress reflex." (PMID 37424900, 2023). "Insulin resistance may cause the upregulation of IL-6, TNF-α, and myostatin and the downregulation of IL-15, FGF-21, and irisin levels." (PMID 37298440, 2023). "Moreover, in research containing 137 obese patients with insulin resistance and high baseline FGF21, FGF21 concentrations were decreased after LSG-induced weight loss." (PMID 36594101, 2023). "Similar to the mechanism of insulin resistance, patients with lower FGF21 levels, possibly reflecting lower FGF21 resistance, could lose weight more easily as a consequence of a healthier and more flexible metabolism." (PMID 36761216, 2023). "FGF21 intervention enhanced adiponectin expression and secretion in adipocytes, thereby upregulating circulating adiponectin levels in mice, while the effects of FGF21 on lowering blood glucose and regulating insulin resistance were partially inhibited when adiponectin was knocked out." (PMID 37576954, 2023). "In obese/overweight people, increased levels of FGF21 were evident and were correlated with triglycerides, insulin concentration, and insulin resistance, suggesting that FGF21 may serve as a biomarker and early indicator of MASLD severity and progression." (PMID 37998747, 2023). "Therefore, a balanced FGF21 level and a reduced myostatin level are also attracting attention as potential therapeutic targets for insulin resistance in T2D." (PMID 36981616, 2023). "However, in another palmitic-acid-induced insulin-resistance model, FGF21 still plays an important role in improving insulin signaling, but with the help of other molecular regulation." (PMID 38069273, 2023). "Moreover, an FGF-21 resistance mechanism, similar to the insulin-resistance seen in diabetes, has been proposed." (PMID 37409233, 2023). "They suggested that reduced FGF19 expression in women with GDM may be related to the pathophysiology of the disease, while elevated FGF21 expression could result from a compensatory response to the insulin resistance observed in GDM." (PMID 38139126, 2023). "In addition, FGF21 normalized the plasma insulin and Homeostatic Model Assessment for Insulin Resistance index, indicating that FGF21 restores insulin sensitivity to that observed in LFCD-fed mice." (PMID 36648330, 2023). "FGF21 The PPARα-fibroblast growth factor 21 (FGF21) axis was activated in the liver of CPT1A deficient mice, which could be used to avoid inflammation, insulin resistance, and weight gain." (PMID 37033619, 2023). "Systemic administration of FGF21 was shown to rectify insulin resistance and obesity." (PMID 37872238, 2023). "FGF21 gene therapy in animals receiving a long-term high-fat-diet feeding or in ob/ob mice showed marked reductions in body weight, adipose tissue hypertrophy and inflammation, hepatic steatosis inflammation and fibrosis, and insulin resistance due to the higher expression of FGF21." (PMID 36552772, 2022). "Furthermore, we find that the expression of neuronal adiponectin is regulated as evidenced by its upregulation in response to rosiglitazone or FGF21 and downregulated in response to insulin resistance." (PMID 36078135, 2022). "Thus, FGF21 protected against renal injury through the improvement of insulin resistance, systemic metabolic disorder, and antifibrotic effect." (PMID 36618930, 2022). "It is suspected that activation of Protein Kinase C (PKC)-ε by a high-fat diet, in combination with increased levels of fetuin B, selenoprotein P and Fibroblast Growth Factor 21 (FGF21) may lead to Insulin Resistance (IR) and hepatosteatosis." (PMID 36005590, 2022).